SNORA80D (small nucleolar RNA, H/ACA box 80D)
Gene: Small nucleolar RNA gene on chromosome 7 (6,016,877 to 6,017,011, forward strand). Ensembl gene ENSG00000207217.
Gene Ontology:
Biological process: RNA processing
Cellular component: nucleolus
Homologues: Orthologues: macaque SNORA80D (95% identical). Paralogues in human: SNORA80B (90% identical), SNORA80A (89% identical), SNORA80C (82% identical), SNORA80E (74% identical).